ENSG00000251974
Gene: Small nucleolar RNA gene on chromosome 2 (86,364,136 to 86,364,265, forward strand). Ensembl gene ENSG00000251974.
Homologues: Orthologues: mouse Gm56029 (63% identical). Paralogues in human: SNORA19 (62% identical).